TNNI2 (troponin I2, fast skeletal type)
Description:
Troponin I is the inhibitory subunit of troponin, the thin filament regulatory complex which confers calcium-sensitivity to striated muscle actomyosin ATPase activity.
Synonyms: FSSV; DA2B; fsTnI; AMCD2B; DA2B1
Tractability: Small molecule: a drug acting on it is in phase 2 or 3 trials; a structure with a bound ligand is known. Antibody: the Human Protein Atlas places it where antibodies can reach.
Gene: Protein-coding gene on chromosome 11 (1,838,981 to 1,841,680, forward strand). Ensembl gene ENSG00000130598.
Subcellular location (Human Protein Atlas): Plasma membrane; Intermediate filaments
Pathways (Reactome):
Muscle contraction: Striated Muscle Contraction
Gene Ontology:
Molecular function: actin binding; protein binding; troponin T binding
Biological process: positive regulation of DNA-templated transcription; skeletal muscle contraction; cardiac muscle contraction
Cellular component: nucleus; troponin complex; cytosol
Genetic constraint (gnomAD): Loss-of-function variants: 14 observed, 26.63 expected, observed/expected ratio (o/e) 0.53, 90% interval 0.35 to 0.82. The upper end of that interval is the gene's LOEUF score, 0.82, which puts it in group 3 of 6, group 1 being the genes least tolerant of losing a copy. Missense variants: 205 observed, 256.65 expected, observed/expected ratio (o/e) 0.8, 90% interval 0.71 to 0.9. Synonymous variants: 126 observed, 102.57 expected, observed/expected ratio (o/e) 1.23, 90% interval 1.06 to 1.42.
Homologues: Orthologues: macaque TNNI2 (98% identical), mouse Tnni2 (97% identical), dog TNNI2 (96% identical), rat Tnni2 (96% identical), guinea pig TNNI2 (94% identical), pig TNNI2 (94% identical), chimpanzee TNNI2 (81% identical), tropical clawed frog tnni2 (72% identical), zebrafish tnni2a.1 (59% identical), zebrafish tnni2b.1 (58% identical), zebrafish tnni2b.2 (57% identical), zebrafish tnni2a.4 (57% identical), and 7 more. Paralogues in human: TNNI1 (57% identical), TNNI3 (54% identical).
Diseases named in the same sentence as TNNI2 in open-access papers:
TNNI2 is named in the same sentence as 30 diseases in open-access papers, as found by Europe PMC text mining. Sharing a sentence is not in itself a finding about the gene and the disease. The quoted sentences say what the papers report.
gastric cancer (5 papers, 2021 to 2023). A primary or metastatic malignant neoplasm involving the stomach. "Overexpression of TNNI2 is associated with recurrence and metastasis in gastric cancer and with poor survival in lung cancer." (PMID 33450964, 2021). "Furthermore, TNNI2 has been identified as a specific biomarker for the prediction of peritoneal metastasis in gastric cancer." (PMID 34907162, 2021). "Furthermore, TNNI2 was reported to have predictive power for metastatic tumor development in gastric cancer." (PMID 34108011, 2021).
distal arthrogryposis (4 papers, 2015 to 2023). A muscle tissue disease characterized by congenital joint contractures of hand and feet. "In contrast, pathogenic variants in homologous genes such as MYH2, TPM2, and TNNI2 that encode parts of the skeletal muscle sarcomere cause muscle diseases affecting skeletal muscle, such as distal arthrogryposis (DA) syndromes and skeletal myopathies." (PMID 37457373, 2023). "TNNI2 is also associated with distal arthrogryposis, types DA1 and DA2B, encoding a subunit of the troponin complex." (PMID 34356068, 2021). "TNNC2 has been implicated in a novel congenital myopathy, TNNI2 and TNNT3 in distal arthrogryposis (DA), and TNNT1 and TNNT3 in nemaline myopathy (NEM)." (PMID 34502093, 2021). "Previous studies have suggested that human mutations in TNNT3, TNNI2, and TPM2 increase the contractility of fast-twitch muscle fibers and cause distal arthrogryposis (DAs) disease." (PMID 26630129, 2015). "To date, TNNI2 has not been implicated in congenital muscle disease, although it has been implicated in the skeletal muscle disorder distal arthrogryposis (DA)." (PMID 34502093, 2021).
pancreatic cancer (3 papers, 2021 to 2023). "However, to date, little is known about the role of TNNI2 and tumorigenesis, and in particular, the association between TNNI2 and pancreatic cancer remains unclear." (PMID 34907162, 2021). "Along with the orphan nuclear receptor ERRα, Tnni2 was identified as a crucial protein contributing to increased cell proliferation, migration and invasion of pancreatic cancer by up-regulation of Sirt1 and downstream Syt8." (PMID 36077344, 2022). "We showed that TNNI2 promoted pancreatic cancer cell proliferation, migration, and invasion in BxPC-3 and PANC-1 cells." (PMID 34907162, 2021). "Thus, we speculated that the TNNI2/ERRα axis was involved in SYT8-mediated pancreatic cancer progression." (PMID 34907162, 2021). "In summary, these results showed a direct correlation between TNNI2 and the ERRα/SIRT1 signaling pathway and its role in altering cell characteristics in pancreatic cancer cell lines." (PMID 34907162, 2021). "In the present study, we used pancreatic cancer cell lines in vitro, an in vivo tumor mouse model, and pancreatic cancer patient tissue samples to identify a novel SYT8-dependent molecular mechanism mediating pancreatic cancer cell proliferation and invasion via TNNI2, ERRα, and SIRT1." (PMID 34907162, 2021).
adenocarcinoma of the lung (2 papers, 2020 to 2021). "Although troponins such as TNNI2 are generally considered to be involved in the regulation of muscle activity, this entire class of proteins has recently been implicated in promoting adenocarcinoma of the lung, pancreas, and stomach." (PMID 34907162, 2021).
arthrogryposis (2 papers, 2018 to 2022). A rare, non-progressive congenital disorder characterized by multiple joint contractures which are present at birth. "Distal arthrogryposis is a cause of syndromic TEV that is characterized by variations in genes that encode for components of the muscle contractile complex (MYH3, TPM2, TNNT3, TNNI2, and MYH8), resulting in muscle contractures." (PMID 30134936, 2018). "However, in the Angus cattle, although there were genes involved in inflammatory disease (OXT) and microcystic adenoma (SHISAL2B), the main function of DEGs was enriched in arthrogryposis (TNNT3 and TNNI2) and myopathy and myasthenic syndrome (MSTN, MYH2, and SLN)." (PMID 35495650, 2022).
Duchenne muscular dystrophy (2 papers, 2022 to 2025). Duchenne muscular dystrophy (DMD) is a neuromuscular disease characterized by rapidly progressive muscle weakness and wasting due to degeneration of skeletal, smooth and cardiac muscle. "Outside of CK and TNNI2, changes in circulating levels of many other proteins have been observed in many NMDs, including the severe myopathy Duchenne muscular dystrophy (DMD)." (PMID 40110646, 2025).
cardiac hypertrophy (1 paper, 2025). "Bulk RNA sequencing revealed significant upregulation of several biomarkers associated with cardiac hypertrophy in BubR1 hypomorphic hearts, including Thbs4, Acta1, Tnni2, and Myh7." (PMID 40607964, 2025).
heart failure (1 paper, 2022). Inability of the heart to pump blood at an adequate rate to meet tissue metabolic requirements. "We also performed the same tests for heart failure in mouse and found that Tnni2 was significantly enriched, which is critical for heart failure." (PMID 34718747, 2022).
insulinomas (1 paper, 2020). "In addition, the log2 3× increase in NFATC1 expression in insulinomas vs. beta cells, together with the hypomethylation of the multiple NFATC1 binding sites in the SYT8/TNNI2 region, suggests that insulin gene transactivation in insulinoma may employ transcriptional signals derived from NFATC1." (PMID 33060578, 2020). "This suggests that NFATC1 may serve as an alternate driver of INS/IGF2 expression in insulinomas, possibly facilitated by looping from the SYT8/TNNI2 locus." (PMID 33060578, 2020).
microcephaly (1 paper, 2017). A congenital or acquired developmental disorder in which the circumference of the head is smaller than normal for the person's age and sex. "Only one patient (DECIPHER ID 265726) does not have microcephaly, which is likely explained by an additional diagnostic de novo mutation in TNNI2, resulting in a complex compound phenotype." (PMID 28053047, 2017).
myopia (1 paper, 2024). "Because the retina is a neural tissue, the expression of numerous genes linked to cardiac muscle (MYBPC3, ACTC1, MYL3, MYH7, MYH7B) or to skeletal muscle (MYL1, SMYD1, TNNI2, MYH1B, ACTA1, TNNT3) presents a conundrum for explaining a mechanism for myopia progression." (PMID 39028695, 2024).
tumor (7 papers, 2014 to 2023). "TNNI2 encodes a component of the troponin complex, present in corneal epithelium, acting as an inhibitor of angiogenesis and tumor suppressor." (PMID 34997134, 2022). "Immunohistochemical analyses of tissue sections showed an increase in TNNI2 and ERRα levels in tumor samples when compared with healthy tissues from patients." (PMID 34907162, 2021). "T-C2 comprised one-fourth of the tumor section and showed relatively high expression of TNNI2 (troponin I2, a fast-twitch skeletal muscle protein) and SYT8 (synaptotagmin 8 and a membrane protein that is important in neurotransmission and hormone secretion), which have been found to promote PC." (PMID 37124494, 2023). "Together, we identified SYT8 to be a central regulator of tumor progression involving signaling via the SIRT1, ERRα, and TNNI2 axis." (PMID 34907162, 2021). "It has been previously shown that expression of TNNI2 inhibits endothelial cell proliferation and angiogenesis (indicated by the T-bar), whereas expression of TNNC1 and TNNI1 promote tumor growth and metastasis (indicated by arrows)." (PMID 29416706, 2018).
cancer (4 papers, 2020 to 2021). A tumor composed of atypical neoplastic, often pleomorphic cells that invade other tissues. "Troponin I2 (TNNI2) was identified as a candidate biomarker for prediction of poor outcomes in various cancers." (PMID 33450964, 2021). "While the roles of SYT8 and TNNI2 have not been broadly described in the context of cancer, their expression levels have been shown to be increased in gastric and bladder-related cancers, indicating that SYT8 and TNNI2 could act as prognostic markers." (PMID 34907162, 2021).
infection (1 paper, 2022). The state of being infected such as from the introduction of a foreign agent such as serum, vaccine, antigenic substance or organism. "Like Tnni2, Atp2a1 mRNA was not apparently upregulated, but we nonetheless detected scattered Atp2a1 protein expression in atrial cardiomyocytes, likely reflecting mosaic infection." (PMID 36076959, 2022). "Atp2a1 and Tnni2 did not appear to be upregulated, but this likely reflects the lower detection background, since the AAV9 infection was mosaic." (PMID 36076959, 2022).
TNNI2 also shares sentences with these, for which no sentence is quoted: Arrhythmia (2 papers); myopathy (2); cardiac arrhythmia (1); co-infection (1); colorectal carcinoma (1); congenital myopathy (1); diabetic cardiomyopathy (1); digestive system disease (1); distal arthrogryposis type 2B (1); distal arthrogryposis types 1 (1); hepatoma (1); ischemia (1); lung carcinoma (1); metastatic tumor (1); nemaline myopathy (1); skeletal myopathies (1).